ESR1 (estrogen receptor 1)
Diseases named in the same sentence as ESR1 in open-access papers (continued):
Sharing a sentence is not in itself a finding about the gene and the disease.
Pruritus (2 papers, 2023 to 2024). Pruritus is an itch or a sensation that makes a person want to scratch. "Clearly, some genes such as AKT1, ALB, BCL2, STAT3, JUN, ESR1, and TNF hold important positions within the network, indicating their strong relevance to the pathogenesis of pruritus and their potential as key targets for drug intervention." (PMID 39606625, 2024).
pyometra (2 papers, 2024 to 2025). "Low transcription levels and expression of ESR1 in the PEH uterus may also be a predisposing factor to pyometra." (PMID 40911583, 2025). "In this context of predisposition to infection, studies verified that female dog uterus with pyometra has low transcription levels of ESR1, suggesting that the low response to estrogen can be related to bacterial infection susceptibility." (PMID 40911583, 2025). "ERα protein expression is increased in the endometrium of cats with pyometra, as observed for the ESR1 gene." (PMID 39457917, 2024).
rectum adenocarcinoma (2 papers, 2020 to 2024). An adenocarcinoma arising from the rectum. "The result illustrated that the hub genes, including NRXN1, ANK2, LPHN2, APOE, TLR8, ESR1, and so on, might be critical for rectum adenocarcinoma, and m6A modification could regulate the abnormal expression of these genes." (PMID 33680913, 2020).
Salmonella Infections (2 papers, 2010 to 2024). Infections with bacteria of the genus SALMONELLA. "In KEGG pathway analysis, it can be found that ESR1 is mainly related to endocrine resistance, the cancer signaling pathway, the estrogen signaling pathway, and Epstein-Barr virus infection, while SIRT1 is mainly related to the FoxO signaling pathway and Salmonella infection." (PMID 38835801, 2024).
sterility (2 papers, 2018 to 2019). "Estrogen Receptor (ESR1) gene null mutation led to sterility in mice." (PMID 30069251, 2018).
tongue cancer (2 papers, 2019 to 2025). A malignant neoplasm affecting the tongue. "Three key bioactive compounds in Rumex dentatus (quercetin, taxifolin, and emodin) target 66 common genes linked with cisplatin and tongue cancer, including EGFR, BCL2, and ESR1 as the most important genes identified." (PMID 39863836, 2025). "According to these parameters ESR1, EGFR, and BCL2 are deemed core targets within the PPI network, highlighting their significance in potential therapeutic interventions which play an important role in the treatment of tongue cancer." (PMID 39863836, 2025). "Those hub genes involved in pathways of cancer are Bcl2, EGFR, ESR1, MMP9, PPARG, and MMP2 and those involved in PI3K-Akt signaling pathways are Bcl2, EGFR, CDK2, and MCL1 these genes are considered therapeutic targets for tongue cancer." (PMID 39863836, 2025).
Turner syndrome (2 papers, 2023). Turner syndrome is a chromosomal disorder associated with the complete or partial absence of an X chromosome. "Currently, there has been research conducted to investigate the impact of ESR1 polymorphisms on the quality of the femoral head in patients with Turner syndrome, revealing that ESR1 rs2234693 is potentially linked to decreased bone mineral density (BMD) in the femoral neck and total hip regions." (PMID 38102657, 2023).
abortion (1 paper, 2013). the ending of pregnancy by removing a fetus or embryo before it can survive outside the uterus. "Association of estrogen receptor alpha gene (ESR1) polymorphisms with spontaneous abortion has been shown in some studies." (PMID 24228243, 2013). "In this study, for the first time, we investigated a possible association between ESR1 variants and spontaneous abortion in the fetal genome." (PMID 24228243, 2013). "Since there has not been sufficient research in relation to effects of fetal genetic variations of ESR1 on reproduction efficiency and risk of spontaneous abortion, more prospective studies with larger sample size in different populations are recommended." (PMID 24228243, 2013). "Our main goal was to study the potential association of spontaneous abortion with the ESR1 gene variations (PvuII and XbaI) in fetal tissue." (PMID 24228243, 2013). "In conclusion, the potential role of ESR1 genetic variation in spontaneous abortion might be valuable in high-risk subjects, and that needs to be confirmed with future studies." (PMID 24228243, 2013).
acne (1 paper, 2024). An inflammatory process of the sebaceous glands which is characterized by comedones, nodules, papules and/or pustules on the skin. "A total of 37 potential targets were predicted by network pharmacology, among which TNF, IL-1B, IL-6, ESR1, PPARG, NFκB1, STAT3, and TLR4 may be the key targets of GA in the treatment of acne." (PMID 38792208, 2024).
Adenomatous Polyposis Coli (1 paper, 2019). "Compared with adjacent normal tissues, tumor samples exhibited hypermethylation of Estrogen Receptor 1, Cadherin 13, Retinoic Acid Receptor Beta, Cell Surface Adhesion Molecule, and Adenomatous Polyposis Coli (ESR1, CDH13, RARB, IGSF4, and APC) genes." (PMID 31390840, 2019).
Arthralgia (1 paper, 2021). "In addition, Estrogen receptor 1 (ESR1) and ESR2 gene polymorphisms have been linked to treatment-related arthralgia." (PMID 33530456, 2021).
asthenozoospermia (1 paper, 2025).
Brain atrophy (1 paper, 2025). Partial or complete wasting (loss) of brain tissue that was once present. "And then the gene set enrichment analysis (GSEA) method was carried out utilizing m6A difference genes, the results indicated that the difference genes were related to neuron synapse, abnormality of prenatal development, brain atrophy, functional motor deficit, ESR1 targets and cell migration." (PMID 40883822, 2025).
bronchopulmonary dysplasia (1 paper, 2020). Bronchopulmonary dysplasia is a chronic respiratory disease that results from complications related to lung injury during the treatment of infant acute respiratory distress syndrome in low-birth-weight premature infants or from abnormal lung development in older infants. "A polymorphism in the estrogen receptor alpha gene ESR1 rs2234693, prostaglandin I2 synthase gene (rs493694) and another polymorphism in the interferon gamma gene rs2430561 is associated with a decreased risk of PDA and bronchopulmonary dysplasia." (PMID 32984222, 2020).
cartilaginous tumors (1 paper, 2011). "We demonstrated expression of ESR1 in a large proportion of various types of cartilaginous tumors." (PMID 22613849, 2011).
dental caries (1 paper, 2022). The decay of a tooth, in which it becomes softened, discolored, and/or porous. "In silico network pharmacology analysis elucidated proteins like ESR1 and IL6 to be majorly involved in biological pathways of dental caries, which also interact with the protective ability of P. betle." (PMID 36557738, 2022).
dermatomyositis (1 paper, 2026). Dermatomyositis (DM) is a type of idiopathic inflammatory myopathy characterized by evocative skin lesions and symmetrical proximal muscle weakness. "Network toxicology analysis suggested that BPA may influence the progression of dermatomyositis by regulating key factors such as AKT1, BCL2, MMP9, ESR1, and INS, thereby affecting apoptosis, immune-inflammatory responses, pathways in cancer, and the PI3K-Akt signaling pathway." (PMID 41911226, 2026).
disorders of sex development (1 paper, 2022). "DMRT3 and OAS3 are involved in human disorders of sex development (DSD) through the control of the ESR1 expression." (PMID 36551704, 2022).
eosinophilic esophagitis (1 paper, 2024). Eosinophilic esophagitis (EoE) is a chronic, allergic disease of the esophagus characterized clinically by symptoms of esophageal dysfunction (including vomiting, dysphagia, feeding disorders, food impaction and abdominal pain) which persist after treatment with proton pump inhibitors (PPIs). "Abnormalities in estrogen genes, including ESR1, have been observed in conditions like eosinophilic esophagitis, influencing esophageal barrier function, caused by increased IL-13." (PMID 38414734, 2024).
Follicular Cyst (1 paper, 2023). Cyst due to the occlusion of the duct of a follicle or small gland. "Our data also showed that the mRNA expressions of ESR1, ESR2, PGR, IGF1Rs and GHSR were changed in follicular cysts." (PMID 37958056, 2023).
gallbladder carcinoma (1 paper, 2012). "Therefore the present study was designed to explore the role of genetic variants in estrogen (ESR1, ESR2) and progesterone (PGR) receptors in conferring risk of gallbladder cancer." (PMID 22808109, 2012). "Thus, carriers of ESR1 haplotypes had a 3.04 times increased risk of gallbladder carcinoma compared with non-carriers, whereas the same haplotypes conferred 2.2 times increased risk for gallstone diseases." (PMID 22808109, 2012). "Given the potential hormonal role in gallbladder diseases, and also the previously explored role of ESR/PGR polymorphisms in female related cancers, we hypothesized that genetic variants in ESR1, ESR2 and PGR genes may have significant impact on the risks of gallbladder cancer." (PMID 22808109, 2012).
germinoma (1 paper, 2011). A malignant germ cell tumor arising in the central nervous system. "However, rather surprisingly, of the ‘top 14’ most frequently reported genes that are hypermethylated in human cancers, all of which were included in our array analysis, only RASSF1A, APC and ESR1 were methylated in the majority of YSTs and almost none were methylated in germinomas." (PMID 21712824, 2011).
gout (1 paper, 2017). A condition characterized by painful swelling of the joints, which is caused by deposition of urate crystals. "Interestingly, three genes (PDZK1, GCKR and HNF4G) associated with urate influenced the risk of gout, but the other five genes (TCF7L2, LRRC16A, ESR1, NRXN2 and ALPK1) did not, suggesting that elevated serum urate concentration is necessary but not sufficient for the pathogenesis of gout." (PMID 28252667, 2017).
hereditary cancer syndromes (1 paper, 2025). "In addition, the presence of hereditary cancer syndromes, PIK3CA or ESR1 mutations, and PD-L1 expression status were indicated." (PMID 41278370, 2025).
hip osteoarthritis (1 paper, 2019). "Our screening identified ESR1, a known regulator in multiple degenerative and aging diseases such as Alzheimer’s, radiographic hip osteoarthritis, aging macula disorder, and cancers." (PMID 31029152, 2019).
HIV-1 infection (1 paper, 2022). The type species of lentivirus and the etiologic agent of acquired immunodeficiency syndrome (AIDS). "This compound could use three targets (ESR1, ESR2 and SERPINB9) to regulate MCM2-TUBB2A, of which MCM2 can effectively block HIV-1 infection of macrophages by inhibiting viral DNA synthesis." (PMID 36534703, 2022).
hypercortisolemia (1 paper, 2022). "Finally, whereas the availability of ESR1 was decreased in hypercortisolemia, prolactin receptor (PRLR) availability was increased." (PMID 35737302, 2022). "The modulation of hormonal receptors, i.e., ESR1 and PRLR, in response to treatment further highlighted the multifactorial effects of prolonged hypercortisolemia in visceral adipose tissue function." (PMID 35737302, 2022).
IgA nephropathy (1 paper, 2020). "ESR1 is a potential therapy target for proteinuria caused by IgA nephropathy through the proliferation of glomerular mesangial cells." (PMID 32025234, 2020).
Incisional hernia (1 paper, 2019). An abdominal hernia that occurs at a site of weakness in the abdominal wall resulting from an incompletely-healed surgical wound. "Some proteins including RNA polymerase III transcription factor, calreticulin, estrogen receptor 1, and Harvey rat sarcoma viral oncogene homolog were found to be higher in cases of postsurgical incisional hernia." (PMID 31024927, 2019).
keloid (1 paper, 2025). An irregularly shaped, elevated mark on the skin caused by deposits of excessive amounts of collagen during wound healing. "ESR1, an estrogen receptor, is potentially reflective of the sex-specific effects of keloids, as cases of worsening keloids in pregnancy or after puberty in females have been documented." (PMID 40835838, 2025).
lung diseases (1 paper, 2023). "ESR1 gene can code estrogen receptors, and studies have found that estrogen signaling may play a key role in lung diseases." (PMID 37274103, 2023).
lung neoplasm (1 paper, 2021). A benign or malignant, primary or metastatic neoplasm involving the lungs.
lupus erythematosus (1 paper, 2022). An autoimmune, connective tissue chronic inflammatory disorder affecting the skin, joints, kidneys, lungs, heart, and the peripheral blood cells. "Estrogen receptor 1 encodes estrogen receptor alpha, and its expression is positively correlated with antinuclear antibody and antireceptor-associated protein antibody and the severity of clinical symptoms of lupus erythematosus." (PMID 36506523, 2022).
malignant myoepithelioma (1 paper, 2016). An infiltrating malignant tumor characterized by the presence of atypical cells with myoepithelial differentiation. "Moreover, simple tubular carcinomas (p = 0.015), complex carcinomas (p = 0.038), carcinomas and malignant myoepitheliomas (p = 0.01) and intraductal papillary carcinomas (p = 0.006) of FFPE samples exhibited significantly lower ESR1 gene expression than the group of lobular hyperplasia." (PMID 27649560, 2016).
mastitis (1 paper, 2025). Inflammation of breast tissue during lactation or postpartum due to an obstructed duct or infection. "Utilizing the PPI network, the topological parameters of Betweenness unDir, Closeness unDir, and Degree unDir were employed to predict the core targets for mint in treating mastitis in dairy cows, which include TNF, IL–6, STAT–3, IL–1β, FGF–2, IFNG, and ESR–1." (PMID 40005889, 2025).
meningitis (1 paper, 2020). A disorder characterized by acute inflammation of the meninges of the brain and/or spinal cord. "More significantly, all vital biotargets of calycosin-anti-meningitis were eventually identified, including EGFR, TNF, EGF, ATM, ESR1, CASP8, NGF." (PMID 33031061, 2020).
mood disturbances (1 paper, 2025). "The haplotypes CG and TA in ESR1 were associated with perinatal mood disturbances." (PMID 40114582, 2025). "In conclusion, the present study indicates that ESR1 variations, which may increase ER-α’s sensitivity to oestrogen, are associated with an elevated susceptibility to perinatal mood disturbances." (PMID 40114582, 2025).
oral submucous fibrosis (1 paper, 2025). "In contrast, in our study on naringenin's antifibrotic effects in oral submucous fibrosis (OSMF) focuses on molecular targets such as MMP2, MMP3, MMP9, TGFB1, ESR1, and SERPINE1, which are crucial in ECM remodeling and inflammation." (PMID 40575446, 2025).
orchitis (1 paper, 2021). Inflammation of one or both testes due to viral or bacterial infections. "Possibly as a compensation, androgen receptor Ar, estrogen receptor Esr1, LH receptor Lhcgr, and Nfe2l2 were all increased during orchitis." (PMID 35111154, 2021).
Peptic ulcer (1 paper, 2024). The term peptic ulcer refers to acid peptic injury of the digestive tract, resulting in mucosal break reaching the submucosa. "The PPI network was constructed for the peptic ulcer genes, the constructed network to show the interactions between peptic ulcer targets proved that the following genes have the higher node degrees; AKT1, TNF, SRC, EGFR, ESR1, PTGS2, MMP9." (PMID 38728332, 2024).
periapical granuloma (1 paper, 2021). Chronic nonsuppurative inflammation of periapical tissue resulting from irritation following pulp disease or endodontic treatment. "MCODE-1 with the highest significance for nuclear receptor transcription pathway and the highest PPI in periapical granuloma was between RXRA, PPARG, ESR1, ESRRA, and NR0B1 proteins." (PMID 34539639, 2021). "PPI revealed the relation between ESR1, ESRRA, and NR0B1 to periapical granuloma." (PMID 34539639, 2021).
Right ventricular cardiomyopathy (1 paper, 2025). Right ventricular dysfunction (global or regional) with functional and morphological right ventricular abnormalities, with or without left ventricular disease. "These male-specific VMPs were linked to genes such as Esr1, and were enriched in arrhythmogenic right ventricular cardiomyopathy related pathways." (PMID 41446098, 2025).
sexual dysfunction (1 paper, 2019). Disturbances in sexual desire and the psychophysiologic changes that characterize the sexual response cycle and cause marked distress and interpersonal difficulty.
skin aging (1 paper, 2025). The gradual irreversible changes in structure of skin that occur as a result of the passage of time.. "Taken together, these findings suggest that the coordinated actions of PPARG, ESR1, and IL6 could serve as promising molecular targets of OFSO for counteracting skin aging hair loss disorders." (PMID 41516153, 2025).
temporomandibular joint disorder (1 paper, 2025). Any condition affecting the anatomic and functional characteristics of the temporomandibular joint. "The COMT, HTR2A, MMPs, IL-1β, IL-6, TNF-α and ESR1 are known to influence the pain perception, inflammation, and joint integrity in temporomandibular joint disorders." (PMID 40291793, 2025).
testicular embryonal carcinoma (1 paper, 2024). A malignant germ cell neoplasm arising from the testis. "Activation of ESR1 increases CCND2 expression and induces proliferation of human testicular embryonal carcinoma NT2/D1 cells." (PMID 39342193, 2024).
vaginal infection (1 paper, 2018). "Therefore, P4-treatment induces neutrophil dependent protection, and E2-treatment reduces neutrophil killing potential during ovulation, probably because of E2 dependent vaginal epithelial cells secretions and induces susceptibility to vaginal infection, which is ESR1 dependent." (PMID 29881378, 2018).
vascular tumor (1 paper, 2024). "According to ESR1 expression, we observed ESR1 was upregulated in vascular tumor zones using the IvyGAP (Ivy GBM Atlas Project) dataset analysis." (PMID 38411438, 2024).